EWSR1 (EWS RNA binding protein 1)
Diseases named in the same sentence as EWSR1 in open-access papers (continued):
Sharing a sentence is not in itself a finding about the gene and the disease.
sarcoma (continued). "Since both EWS-FLI1 and EWS-WT1 fusion oncogenes contain the N-terminus of EWSR1, this approach targets a central node shared between different clinical manifestations of sarcoma: aberrant transcription driven by the condensation of the N-terminus of EWSR1." (PMID 36483537, 2022). "Based on whole transcriptome sequencing, EWSR1-PATZ rearranged sarcomas are different from other EWSR1-related sarcomas." (PMID 34203801, 2021). "Assessment of partner genes in EWSR1 fusion positive sarcomas found that fusion partner genes were most prevalent on chromosome 11, driven by FLI1." (PMID 34021224, 2021). "Angiomatoid fibrous histiocytoma, primary pulmonary myxoid sarcoma, and myoepithelial tumours of soft tissue are exceptionally rare forms of sarcoma that harbour translocations of the EWSR1 gene (EWSR1-CREB, EWSR1-ATF1) or the FUS gene (FUS-AFT1)." (PMID 33669307, 2021). "The fusion gene of ATF1 with EWSR1 or FUS is frequently reported in sarcomas including angiomatoid fibrous histiocytoma and clear cell sarcoma, which are relatively chemoresistant." (PMID 36860287, 2021). "Emerging evidence suggests unique molecular characteristics and chemotherapy sensitivities in EWSR1-NFATc2 fusion positive sarcomas." (PMID 34021224, 2021). "NFATc2-sarcomas include sarcomas with EWSR1–NFATc2, which commonly show an EWSR1 amplification pattern on fluorescence in situ hybridization, and FUS-NFATc2 fusions." (PMID 33919988, 2021). "Historically, EWSR1-NFATc2 fusion positive sarcomas have been classified as a member of the Ewing family of sarcomas; however, growing evidence suggests that EWSR1-NFATc2 fusion positive sarcomas should be considered separate from standard Ewing sarcomas." (PMID 34021224, 2021). "Here, data from 1024 EWSR1 fusion positive sarcomas demonstrates the uniqueness of EWSR1-NFATc2 fusion cancers from other cancers in the Ewing family." (PMID 34021224, 2021). "EWSR1:PATZ1 fusions have also been reported in a subset of sarcomas occurring across a wide range of ages, with a predilection for occurrence in the chest wall, showing substantial heterogeneity in their morphology and immunoprofile." (PMID 34417833, 2021). "Comprehensive genomic profiles of 1024 EWSR1 fusion positive sarcomas, including 14 EWSR1-NFATc2 fusions, were identified in the FoundationCore® database." (PMID 34021224, 2021). "Chi-squared analysis demonstrated a statistical difference between EWSR1-FLI1/ERG and EWSR1-NFATc2 positive sarcomas across all genes included in the dataset (p < 0.001)." (PMID 34021224, 2021). "EWSR1-PATZ-rearranged sarcoma seems to be a separate entity with a wide clinicopathological spectrum." (PMID 34203801, 2021). "Sarcomas are mesenchymal tumours that often arise and develop as a result of chromosomal translocations, and for several forms of sarcoma the EWSR1 gene is a frequent translocation partner." (PMID 33669307, 2021). "FUS and EWSR1, which are the most common fusion partners in translocated fusion oncoproteins and characterize several sarcoma histologies, are drivers of the three-dimensional chromatin structure." (PMID 34299136, 2021). "Because various types of sarcomas express fusion genes that have N terminus of EWSR1 including Thr 79, this study has the potential to reveal a universal mechanism for the pathogenesis underlying all EWSR1 fusion protein-expressing sarcomas." (PMID 33293370, 2021). "As expected, lung tumors with driver fusions harbored mostly EML4/ALK fusions, sarcomas were driven mostly by EWSR1-related and PAX3/FOXO1 fusions, while hematologic malignancies with a spectrum of BCR/ABL1, KMT2A-related, and IGH/MYC fusions." (PMID 33889297, 2021). "We also present a case of a 58-year-old male patient with metastatic EWSR1-NFATc2 fusion positive sarcoma who achieved 47 months of disease stabilization when treated with combination mTOR and VEGF inhibition." (PMID 34021224, 2021).
sarcoma (continued). "As with other sarcomas, each case of CCS is primarily driven by a single mutation particular to each tumour and for CCS genomic translocation results in the fusions of EWSR1 with ATF1 or, rarely, with CREB1." (PMID 33669307, 2021). "Molecularly, EWSR1-NFATc2 fusion positive sarcomas are distinct from other EWSR1 fusion positive sarcomas as measured by gene expression and methylation profiles." (PMID 34021224, 2021). "Little data exists to guide the clinical care of EWSR1-NFATc2 fusion positive sarcomas due to their rarity." (PMID 34021224, 2021). "The last G4 structure included in this group is found in the EWS RNA binding protein 1, EWSR1, one of the genes most commonly involved in sarcoma translocations, rendering novel transcription factors with tumoral effects." (PMID 33255335, 2020). "Chromosome 22-specific inversions that translocate the transcription factor EWSR1 with PATZ1 have been observed in various sarcomas." (PMID 32496219, 2020). "Conversely, transcriptomes of CIC-DUX4 fusion and other CIC rearranged sarcomas compared with ES family of tumors (ESFTs) with EWSR1-ETS fusions show little overlap in differentially expressed genes, supporting the distinction of these tumors from ESFTs." (PMID 32155762, 2020). "While FLI1 is unable to confirm EwS cases with FET–non-FLI1 translocations, NKX2-2 and PAX7 lack specificity and can be even strongly expressed in close morphological mimics such as EWSR1-NFATc2-positive sarcomas." (PMID 32164354, 2020). "It turned out that many sarcomas especially harbor specific fusion genes that now can be utilized to differentiate between sarcoma entities, for example, the EWSR1-FLI fusion gene for the differential diagnosis of small round blue cell tumors." (PMID 31491926, 2019). "Desmoplastic small round cell tumor (DSRCT) is a rare, aggressive, and poorly investigated simple sarcoma with a low frequency of genetic deregulation other than an Ewing sarcoma RNA binding protein 1 (EWSR1)-Wilm’s tumor suppressor (WT1) translocation." (PMID 30486883, 2018). "The set of morphological mimics also comprised CIC-DUX4-, BCOR-CCNB3-, and EWSR1-NFATc2-translocated sarcomas, which proved to be distinct entities as determined by unsupervised principal component analysis (PCA)." (PMID 29416716, 2018). "This publication included results from sarcoma samples analysed on a pilot array including only two fusion genes, EWSR1-FLI and EWSRI-ERG." (PMID 23967081, 2013). "The induction of several types of sarcomas, such as EWSR1, MLS, and alveolar rhabdomyosarcoma, by overexpression of specific oncogenic fusion proteins in multipotent mesenchymal cells has been documented." (PMID 22570737, 2012). "The FET-protein family includes FUS (fused in sarcoma, also called TLS (translocated in liposarcoma)), EWS (Ewing sarcoma breakpoint 1, also called EWSR1), and TAF15 (TATA box binding protein associated factor 68 kDa)." (PMID 23049996, 2012). "Submitted] - reclassified as myoepthelioma-like sarcoma - had an EWSR1/NFATC2 fusion, adding to the growing morphological spectrum of this recently described gene fusion." (PMID 22588017, 2011). "The EWSR1 gene is involved in a number of different sarcomas as a result of chromosomal translocations." (PMID 17912356, 2007). "Advances in molecular genetics have refined the definition of ES, which is now strictly characterized by FET::ETS fusions—most commonly EWSR1::FLI1—thereby distinguishing it from the heterogeneous group of “Ewing-like” sarcomas that lack these canonical rearrangements." (PMID 41514642, 2025). "Diagnoses included ASPSCR1::TFE3 alveolar soft part sarcoma; WWTR1::CAMTA1 epithelioid hemangioendothelioma; INI-1 deficient epithelioid sarcoma; EWSR1::NR4A3 extra-skeletal myxoid chondrosarcoma; and low-grade ARHGAP23::FER spindle cell malignancy, a novel fusion-driven sarcoma." (PMID 39941809, 2025).
sarcoma (continued). "Fluorescence in situ hybridization (FISH) studies for EWSR1 gene rearrangement or whole transcriptome exome sequencing can help assist in excluding an EWSR1-rearranged sarcoma, round cell sarcomas with BCOR alterations, and small round cell sarcomas, NOS, respectively." (PMID 40599504, 2025). "In summary, our results show that the PF1095 cell line is an invaluable tool to better understand EWSR1::POU2AF3 sarcomas and to test potential new combination therapies that might increase therapeutic efficacy." (PMID 40134582, 2025). "Furthermore, they provide a strong rationale for the use of PROTACs in targeting gene fusions in paediatric sarcoma such as EWSR1::FLI1 and PAX3::FOXO1." (PMID 40983796, 2025). "Definitive classification generally requires demonstration of a pathognomonic gene rearrangement by molecular methods, i.e., commonly FISH (EWSR1 break-apart), RT-PCR for specific fusion transcripts, or targeted next-generation sequencing panels that detect a broad range of sarcoma fusions." (PMID 40978877, 2025). "The authors have considered the two examples as unclassified EWSR1::CREM fusion sarcomas." (PMID 39249507, 2024). "Furthermore, approximately 50% of myoepitheliomas have translocations involving the EWSR1 gene, such as EWSR1::POU5F1 sarcoma, and myoepithelioma can also exhibit positive expression of CD99 and NKX3.1, posing a significant diagnostic challenge." (PMID 38254207, 2024). "In summary, the differential diagnosis of EWSR1/FUS::NFATC2 sarcoma is complex with many pitfalls." (PMID 38254207, 2024). "The fusion breakpoints and fusion types in EWSR1/FUS::NFATC2 sarcoma may impact the tumor's biological behavior and prognosis." (PMID 38254207, 2024). "Here, we describe three new examples of rare GFs in sarcoma, further expanding the growing catalogue of EWSR1 partner genes that may define specific entities with distinct prognostic and therapeutic implications." (PMID 38339014, 2024). "Furthermore, the EWSR1 gene is involved in gene fusions in at least 11 sarcoma entities, suggesting that the relevant functionality of the EWSR1 protein can cooperate with different fusion partners and in different cellular contexts." (PMID 38611033, 2024). "Overall, it is reasonable to speculate that these functional properties of EWSR1 may serve as the basis for its widespread involvement in sarcoma tumorigenesis." (PMID 38611033, 2024). "Moreover, beyond sarcoma, EWSR1 GFs have also been described in a subset of mesothelioma and specific carcinomas and myoepithelial tumors." (PMID 38339014, 2024). "In addition, extraskeletal myxoid chondrosarcoma (EMC) needs to be differentiated from EWSR1/FUS::NFATC2 sarcoma." (PMID 38254207, 2024). "FUS::NFATC2 sarcoma has a worse prognosis than EWSR1::NFATC2 sarcoma." (PMID 38254207, 2024). "FISH and NGS play an important role in the diagnosis of EWSR1/FUS::NFATC2 sarcoma." (PMID 38254207, 2024). "Such promiscuity of EWSR1 in translocation-driven sarcomas and other tumors may be explained by the high propensity to breakage of this locus in certain cellular contexts." (PMID 38339014, 2024). "Therefore, histological and immunohistochemical examinations can provide important references for the diagnosis of EWSR1/FUS::NFATC2 sarcoma." (PMID 38254207, 2024). "This category includes EWSR1/FUS::NFATC2 sarcomas and EWSR1::PATZ1 sarcomas." (PMID 36983010, 2023). "Immunohistochemically, CD99 is diffusely expressed in 50% of EWSR1/FUS::NFATC2 sarcoma cases." (PMID 36983010, 2023). "These mainly comprise EWSR1::NFATC2 and FUS::NFATC2 sarcomas and EWSR1::PATZ1 sarcomas." (PMID 36941503, 2023). "FUS and EWSR1 can replace each other and occur in other sarcomas, while DDIT3 is unique to MLPS." (PMID 36983010, 2023). "Additionally, recurrent fusion gene amplification is almost exclusively detected in the EWSR1::NFATC2-rearranged sarcomas." (PMID 36555836, 2022).
sarcoma (continued). "Additionally, recurrently detected secondary fusion transcripts in patients diagnosed with EWSR1-NFATC2-positive sarcoma were confirmed (COPS4-TBC1D9, PICALM-SYTL2, SMG6-VPS53, and UBE2F-ALS2)." (PMID 36232302, 2022). "Three of them (COPS4-TBC1D9, SMG6-VPS53, and UBE2F-ALS2) could not be detected in the other EWSR1-rearranged patients of cohort II and are thus specifically expressed in sarcomas with an EWSR1-NFATC2 fusion." (PMID 36232302, 2022). "Importantly PDGF ligands and/or receptors are frequently upregulated in ES and their expression correlates with the activity of the EWSR1/FLI1 fusion in sarcoma tissues." (PMID 35454895, 2022). "Higher expression levels of fusion transcripts found in EWSR1::NFATC2-rearranged sarcomas could also be an explanation for the malignant behavior." (PMID 36555836, 2022). "Further assessment of the molecular differences between EWSR1-NFATc2 and other EWSR1 fusion positive sarcomas may shed light on the disparity of response to chemotherapeutics while providing insight into new treatment methods for these patients." (PMID 34021224, 2021). "Furthermore, we report a clinical case of a patient with an EWSR1-NFATc2 fusion positive sarcoma whose tumor was stabilized by mTOR combination therapy." (PMID 34021224, 2021). "EWSR1-NFATc2 fusion positive sarcomas exhibited a relatively stable genome." (PMID 34021224, 2021). "EWSR1-NFATc2 fusion positive sarcomas are molecularly distinct entities with overactive mTOR signaling; which may be therapeutically targetable." (PMID 34021224, 2021). "Pathway analysis identified a significant activation of the mTOR pathway in EWSR1-NFATc2 positive sarcomas compared to either EWSR1-ETS or CIC-DUX4 positive sarcomas (EWSR1-NFATc2 vs. EWSR1-ETS: z-score = 1.6, p = 0.002; EWSR1-NFATc2 vs. CIC-DUX4: z-score = 1, p < 0.001)." (PMID 34021224, 2021). "Additionally, we evaluate altered pathways using transcriptomic data and highlight the importance of the mTOR pathway in EWSR1-NFATc2 fusion positive sarcomas." (PMID 34021224, 2021). "Given the suggested activation of mTOR in EWSR1-NFATc2 fusion positive sarcomas, and the conservation of the primary transactivation and regulatory domains of NFATc2 in EWSR1-NFATc2 fusion, we proceeded to assess the role of NFATc2 overexpression on mTOR in a tumor agnostic fashion." (PMID 34021224, 2021). "EWSR1 rearrangement is broadly available for subtyping sarcomas." (PMID 33713576, 2021). "Furthermore, EWSR1 is involved in several other sarcomas, but then with different partners, for instance extraskeletal myxoid chondrosarcoma (NR4A3), clear cell sarcoma (ATF1, CREB1), and myxoid liposarcoma (DDIT3)." (PMID 23967081, 2013). "Despite the involvement of EWSR1 in these diverse sarcomas, the in vivo function of wild type EWSR1 remains unclear." (PMID 17912356, 2007). "Furthermore, many studies highlight the promise of kinase inhibitors such as larotrectenib in treating NTRK-fusion-positive sarcomas and DNA minor groove-binding agents like trabectedin or mithramycin as potential inhibitors of EWSR1::FLI1-mediated transcription." (PMID 38228904, 2024). "However, other tumors such as EWSR1::POU5F1 sarcoma and rare myoepithelial sarcoma may also show separation with amplification signals in FISH testing, but they are accompanied by amplification at the 3' end or other locations." (PMID 38254207, 2024). "Since it was recently shown that, apart from the pathognomonic fusion, also secondary fusions may show oncogenic potential in EWSR1-rearranged sarcomas, it would be worthwhile to further investigate the functional role of COPS4-TBC1D9, SMG6-VPS53, and UBE2F-ALS2 in EWSR1-NFATC2-positive patients." (PMID 36232302, 2022). "This phenomenon is described in several cases of EWSR1/FUS::NFATC2-rearranged sarcomas in which symptoms were present for years before diagnosis, suggesting that a pre-existing low-grade component may have undergone biological progression in a subset of patients." (PMID 36555836, 2022).
sarcoma (continued). "As with the sarcomas in which EWSR1:PATZ1 has been reported, the morphological variety, inconclusive immunoprofile and wide range of age at presentation are striking features that may account for the fact that these tumors have not been identified as a clear entity until now." (PMID 34417833, 2021). "While this finding is not suggestive of exquisite stabilization of EWSR1-NFATc2 fusion positive sarcomas to mTOR combination therapy, when linked with the other presented evidence a case could be made for mTOR as a potential therapeutic target in this disease." (PMID 34021224, 2021). "In sarcomas, CDKN2A alterations, reported in 71% of EWSR1::PATZ1 fusion cases in a series of 11 patients, are associated with aggressive phenotypes and poorer outcomes." (PMID 40575153, 2025). "A recent study investigated the molecular profiling of ped/AYA sarcomas and noted alterations in several DDR genes, including SLFN11, EWSR1, BRCA1, BRCA2, and MLH1." (PMID 40563612, 2025). "Many sarcomas are driven by fusion proteins, which most commonly include FUsion in malignant lypoSarcoma (FUS), EWS RNA Binding Protein 1 (EWSR1) and TATA-box binding protein Associated Factor 15 (TAF15) as partners." (PMID 37828086, 2025). "An initial diagnosis of sarcoma NOS in the abdomen and trunk was classified as ES and extraskeletal myxoid chondrosarcoma (EMC) based on the fusion genes EWSR1::FLI1 and NR4A3::EWSR1, respectively." (PMID 40755265, 2025). "While EWSR1::ATF1 and fused in sarcoma::activating transcription factor 1 (FUS::ATF1) fusion genes can be detected in AFH, they are rarely found in PPMS cases." (PMID 38421462, 2024). "Although some gene fusions are very specific to a particular tumor type (e.g. EWSR1::FLI1 in Ewing sarcoma), other gene fusions are much more non-specific, such as ETV6::NTRK3, which can be seen not only in sarcomas but also in leukemias or carcinomas." (PMID 38228904, 2024). "Recently, a number of rare EWSR1 partners were reported in a genomic study of tumor cases profiled with NGS panels, with most of them being sarcomas but with carcinomas also present." (PMID 38339014, 2024). "EWSR1::NFATC2 rearranged sarcomas are a group of rare round, undifferentiated sarcomas with clinicopathological features different from those of Ewing's sarcoma (ES) family and other non-ES sarcomas." (PMID 38254207, 2024). "In our review of the four cases reported in this study and previously published cases, almost all reported cases of EWSR1::NFATC2 sarcoma exhibited the FISH pattern with separation of red and green signals accompanied by 5' amplification of the EWSR1 locus." (PMID 38254207, 2024). "Fusion analysis revealed two FUS::NFATC2 rearrangements in two cystic lesions and three EWSR1::NFATC2 rearrangements in one complex cystic lesion and two sarcomas." (PMID 36555836, 2022). "More than 25 types of sarcoma and leukemia are characterized by fusion oncogenes formed between one of the FET genes (FUS, EWSR1, or TAF15) as 5′ partner and one of more than 30 alternative transcription factor-coding genes as 3′ partner." (PMID 35186752, 2022). "FET fusion oncoproteins containing one of the FET (FUS, EWSR1, TAF15) family proteins juxtaposed to alternative transcription‐factor partners are characteristic of more than 20 types of sarcoma and leukaemia." (PMID 35182012, 2022). "FET family proteins comprising FUS, EWSR1, and TAF15 are not only involved in neurodegenerative disease but also act as oncoproteins in sarcoma or leukemia by chromosomal translocation." (PMID 36194562, 2022). "In comparison to EWSR1-FLI1 and EWSR1-ERG, the secondary genomic landscape of EWSR1-NFATc2 fusion positive sarcomas is significantly different and appears to be driven by genes related to the mTOR pathway." (PMID 34021224, 2021). "The EWSR1 gene is a member of the TET (also known as FET) family, including Fused in sarcoma/Translocated in Liposarcoma (FUS/TLS) and TATA-box binding Associated Factor 15 (TAF15)." (PMID 34612781, 2021).